TGM2 (transglutaminase 2)
Diseases named in the same sentence as TGM2 in open-access papers (continued):
Sharing a sentence is not in itself a finding about the gene and the disease.
osteosarcoma (3 papers, 2021 to 2025). A usually aggressive malignant bone-forming mesenchymal neoplasm, predominantly affecting adolescents and young adults. "Moreover, previous study revealed that TGM2 expression was enhanced in cisplatin-resistant OS cells and its deficiency elevated the chemosensitivity of osteosarcoma to cisplatin." (PMID 33435987, 2021). "As to osteosarcoma, knockdown of TGM2 promotes the chemosensitivity of osteosarcoma cells by inhibiting Akt and MAPK signaling pathways." (PMID 36872331, 2023). "In addition, TGM2 has been revealed to participate in the initiation and modulation of the mineralization process in osteosarcoma cell line SAOS-2." (PMID 36872331, 2023). "Additionally, TGM2 promotes metastatic phenotypes of osteosarcoma cells and is responsible for osteosarcoma stem-like properties." (PMID 36872331, 2023). "Besides, previous report revealed that TGM2 promoted the progression of osteosarcoma." (PMID 33435987, 2021).
papillary thyroid carcinoma (3 papers, 2021 to 2026). "Correlation between TGM2 expression and clinicopathological features in patients with papillary thyroid cancer (n = 92)." (PMID 33738254, 2021). "Notably, we identified a protein interaction between TGM2 and HK1 that was significantly upregulated in the papillary thyroid carcinoma cell line TPC-1." (PMID 41571643, 2026).
tuberculosis (3 papers, 2014 to 2023). A chronic, recurrent infection caused by the bacterium Mycobacterium tuberculosis. "Following our recent report indicating that genetic and pharmacological inhibition of transglutaminase 2 (TG2) restricts Mycobacterium tuberculosis (Mtb) replication in macrophages, we aimed to investigate the potentials of the TG2 inhibitors cystamine and cysteamine as HDTs against TB." (PMID 32038614, 2019).
abdominal aortic aneurysm (2 papers, 2021 to 2024). Enlargement and ballooning of the vessel that supplies arterial blood to the abdomen, pelvis and legs. "Previously published work has indicated that transcripts encoding transglutaminase 2 (TG2) increase markedly in a rat model of abdominal aortic aneurysm." (PMID 34617062, 2021).
acute kidney injury (2 papers, 2022 to 2023). Sudden and sustained deterioration of the kidney function characterized by decreased glomerular filtration rate, increased serum creatinine or oliguria.
aneurysm (2 papers, 2021 to 2024). Bulging or ballooning in an area of an artery secondary to arterial wall weakening. "In view of the possibility that FXIII-A might act redundantly with TG2 to influence aneurysm development, aortic dilatation was also measured 6 weeks after CaCl2 treatment in F13a1–/– mice and Tgm2–/–/F13a1-/- mice." (PMID 34617062, 2021). "Although the cause of death after laparotomy in Tgm2–/–/F13a1–/– mice seemed to be unrelated to aneurysm development, it seemed possible that Tgm2–/–/F13a1–/– mice that would otherwise have developed a large AAA were more likely to die prematurely than those developing a small aneurysm." (PMID 34617062, 2021). "Because FXIII-A might act redundantly with TG2 to mediate protection or repair, we also induced aneurysms in Tgm2–/–/F13a1–/– and F13a1–/– mice." (PMID 34617062, 2021). "In summary, while the properties of aortas from F13a1–/– and Tgm2–/– single knockout mice appeared similar to C57Bl/6J wild-type mice, there were detectable differences in the basal state of Tgm2–/–/F13a1–/– double knockout aortas that could affect their response to aneurysm development." (PMID 34617062, 2021). "Therefore, to address the roles of TG2 and FXIII-A in aneurysm development, we have induced aneurysms in the infrarenal aorta ofTgm2–/– knockout, F13a1–/– knockout, and Tgm2–/–/F13a1–/– double knockout mice." (PMID 34617062, 2021). "In view of the high mortality associated with laparotomy in mice lacking FXIII-A, and the lack of evidence that FXIII-A protects against aneurysm development, aneurysm development at 24 weeks was not assessed in either F13a1–/– or Tgm2–/–/F13a1–/– mice." (PMID 34617062, 2021). "A comparable death rate among NaCl-treated (sham-operated) Tgm2–/–/F13a1–/– mice indicated that deaths were not a consequence of aneurysm development." (PMID 34617062, 2021). "However, vessels from Tgm2–/– mice, but not wild-type mice, continued to dilate up to 6 months after injury and by 24 weeks, a greater number of Tgm2–/– mice had developed aneurysms (16/17 vs 10/19; P = .008)." (PMID 34617062, 2021).
Anxiety (2 papers, 2023 to 2026). Intense feelings of nervousness, tension, or panic often arise in response to interpersonal stresses. "We provide evidence that the deletion of microglial Tgm2 causes impaired synaptic pruning, less anxiety and defects in cognition in mice." (PMID 36878712, 2023).
autism (2 papers, 2013). Persistent deficits in social interaction and communication and interaction as well as a markedly restricted repertoire of activity and interest as well as repetitive patterns of behavior. "In this protein family, another member TGM2 is related with autism spectrum disorders, indicating that there is a possibility that TGM3 has underlying effect on mechanism of autism." (PMID 23369322, 2013).
bipolar disorder (2 papers, 2012 to 2025). A disorder of the brain that causes unusual shifts in mood, energy, activity levels and the ability to carry out day-to-day tasks. "In the female bipolar disorder material a significant association result was found for rs6023059 (corrected p-value = 0.023; odds ratio (OR) 0.681, 95% confidence interval (CI) 0.570–0.814), a single nucleotide polymorphism (SNP) placed downstream of the gene coding for transglutaminase 2 (TGM2)." (PMID 22389694, 2012). "After correcting for multiple testing, a significant association was found for rs6023059, placed in the downstream genomic region of TGM2, in women with bipolar disorder." (PMID 22389694, 2012). "Based on hub genes, 49 diseases were predicted by DisGeNET, bipolar disorder was disease predicting by SHANK2 and TGM2 simultaneously." (PMID 41142802, 2025).
brain tumor (2 papers, 2024). "Using tissue microarrays of 158 brain tumour samples, we assessed CD3, CD4, CD8, CD20, CD138, Granzyme B (GzmB), 5-Lipoxygenase (5-LOX), Programmed Death-Ligand 1 (PD-L1), O-6-Methylguanine-DNA Methyltransferase (MGMT) and Transglutaminase 2 (TG2) expression by immunohistochemistry (IHC)." (PMID 38816839, 2024).
breast invasive ductal carcinoma (2 papers, 2013 to 2016). "In GSE14548 dataset, including a total of 34 stromal samples referring to stroma adjacent to normal mammary cells, DCIS or invasive ductal carcinoma (IDC) we found TGM2 was consistently over-expressed in tumor-associated stroma with respect to stroma associated with normal mammary cells." (PMID 27600076, 2016). "Transglutaminase 2 (TG2) expression in cytoplasm and stroma of breast invasive ductal carcinoma (IDC)." (PMID 24058567, 2013).
cholestasis (2 papers, 2017 to 2024). Impairment of the bile flow caused by obstruction within the liver, or outside the liver in the bile duct system. "Our results showed that the deletion of Tgm2 adversely affected the functionality and maturity of the proliferative cholangiocytes in DR, thus leading to more severe cholestasis during DDC‐induced liver injury." (PMID 38623945, 2024). "Tgm2−/− mice exhibited aggravated DDC‐induced cholestasis, as evidenced by elevated levels of cholestatic markers in the plasma, such as alkaline phosphatase (ALP) and gamma‐glutamyltransferase (γ‐GT)." (PMID 38623945, 2024). "In conclusion, our findings demonstrate that the deletion of Tgm2 affects the development and function of proliferated BECs during DR, resulting in more severe cholestasis." (PMID 38623945, 2024). "Additionally, the level of DDC‐induced cholestasis and hepatocyte injury was relieved in the Tgm2−/− + rhBMP7 group, as indicated by reduced levels of ALP, γ‐GT, TBIL, and ALT." (PMID 38623945, 2024). "Though few significant differences in biliary development were found between Tgm2−/− and WT mice in normal feeding, deficiency of Tgm2 in mice caused the damage of the hallmarks of normal biliary cells such as OPN, acTUB, TGR5, and SSTR2 and even more severe cholestasis in DDC‐induced DR." (PMID 38623945, 2024).
cognitive decline (2 papers, 2024 to 2025). "Microglia are the main source of Tgm2 in the brain, and the previous study has found that knockout of Tgm2 in microglia in mice leads to synaptic remodeling impairment and cognitive decline, indicating that Tgm2 is crucial for normal neural development." (PMID 39749582, 2025).
conjunctivitis (2 papers, 2010 to 2022). Inflammation of the conjunctiva of the eye. "In prior investigations, TMG2 from guinea pig liver has been shown to increase the PLA2 activity of bovine pancreatic PLA2, and dual inhibitors of TGM2 and sPLA2 reduced ocular inflammation in a rabbit model of allergen-induced conjunctivitis." (PMID 20052409, 2010).
injury (2 papers, 2011 to 2022). Damage inflicted on the body as the direct or indirect result of an external force, with or without disruption of structural continuity. "Transglutaminase 2 (TG2) is a calcium-dependent transamidating acyltransferase enzyme of the protein-glutamine γ-glutamyltransferase family implicated in kidney injury." (PMID 35740367, 2022).
interstitial lung disease (2 papers, 2023 to 2025). A diverse group of lung diseases that affect the lung parenchyma. "In view of the previous persuasive data concerning the role of TGM2 in interstitial lung diseases, it is likely that TGM2 would exert an important influence in the pulmonary complications in scleroderma." (PMID 39800950, 2025).
keloid (2 papers, 2017 to 2022). An irregularly shaped, elevated mark on the skin caused by deposits of excessive amounts of collagen during wound healing. "TGM2 may be able to act as an auxiliary diagnostic indicator for keloids." (PMID 35669563, 2022). "The results revealed that the expression of TGM2 was significantly increased in keloid tissues compared with the corresponding normal skin tissues." (PMID 35669563, 2022). "Although the study of TGM2 in keloid pathogenesis lacks in-depth research, it is reasonable to believe that TGM2 is a very promising mechanistic molecule in keloids based on its regulation of fibroblast and extracellular matrix in tumors." (PMID 35669563, 2022). "TGM2 has been confirmed in previous studies to be associated with fibrosis and tumorigenesis; however, the role of TGM2 in keloids has not been adequately reported." (PMID 35669563, 2022). "To investigate the possible molecular mechanism of TGM2 in keloids, we selected key molecules involved in extracellular matrix formation, collagen formation, hypoxia and epithelial mesenchymal transition to conduct correlation analysis with TGM2 in the GSE145725 dataset." (PMID 35669563, 2022). "Besides, TGM2 was significantly upregulated in clinical keloid samples compared to normal skin tissues." (PMID 35669563, 2022). "This study finally identified TGM2 as a promising biomolecule in keloids." (PMID 35669563, 2022). "Therefore, TGM2 may be developed as a new research hotspot and target for the prevention, diagnosis and treatment of keloids." (PMID 35669563, 2022). "In addition, we detected TGM2 expression in clinical keloid tissues via RT-qPCR and IHC." (PMID 35669563, 2022). "Subsequently, we analyzed the correlation between TGM2 and the TGF-beta signaling pathway in keloids." (PMID 35669563, 2022). "ROC curves indicated that the AUC values of TGM2 in GSE7890, GSE145725 and GSE117887 were 0.840, 0.922 and 1.000, respectively, indicating that TGM2 has a robust performance in the diagnosis of keloids." (PMID 35669563, 2022). "However, the role of TGM2 in keloids has not been adequately reported in the current literature, which may provide a new direction for molecular studies of keloids." (PMID 35669563, 2022).
kidney (2 papers, 2022 to 2023). "Consistent with its key molecular role, TGM2_v2 transcript has emerged as significantly overexpressed in PCa patients’ biopsies compared to prostatitis when confronted with the canonical long form of TG2." (PMID 37160910, 2023).
liver cancer (2 papers, 2023 to 2025). An epithelial or non-epithelial malignant neoplasm that arises from the liver. "A mouse liver cancer cell line that we developed depends exclusively on TGM2 for protein polyamination." (PMID 41142754, 2025). "We performed polyamination reactions using whole cell lysates from a mouse liver cancer cell line with elevated TGM2 expression." (PMID 41142754, 2025).
lung adenocarcinoma (2 papers, 2022 to 2024). A carcinoma that arises from the lung and is characterized by the presence of malignant glandular epithelial cells. "We found that TGFB1, ENG, TGM2, TBXA2R, HSPG2, and PTPRS were significantly upregulated in lung adenocarcinoma cells." (PMID 36249427, 2022).
mastocytosis (2 papers, 2021 to 2023). A clonal myeloproliferative neoplasm characterized by the proliferation and accumulation of neoplastic mast cells in one or multiple organs or organ systems. "Furthermore, it was shown that in children with mastocytosis, MCs may migrate to the skin and BM as a result of the upregulation of CCL2/chemokine receptor 2 (CCR2) and vascular cell adhesion molecule (VCAM-1), and they may induce the expression/activation of transglutaminase 2 (TG2)." (PMID 37108184, 2023). "Interestingly, it was shown that in children with mastocytosis, MCs may migrate to the skin and BM as the result of upregulation of CCL2/chemokine receptor 2 (CCR2) and vascular cell adhesion molecule (VCAM-1) and they may induce the expression/activation of transglutaminase 2 (TG2)." (PMID 33806685, 2021).
Peritoneal Fibrosis (2 papers, 2024 to 2025). Disorder characterized by a wide range of structural changes in PERITONEUM, resulting from fibrogenic or inflammatory processes. "Genetic deletion of transglutaminase 2 decreases TGF-β expression and suppresses peritoneal fibrosis and angiogenesis in a chlorhexidine gluconate-induced murine model of peritoneal fibrosis associated with attenuated EMT." (PMID 39201294, 2024).
preeclampsia (2 papers, 2022 to 2024). Preeclampsia is a hypertensive disorder of pregnancy that is characterized by new-onset hypertension with proteinuria presenting after 20 weeks of gestation, and depending on mild or severe forms may initially present with severe headache, visual disturbances, and hyperreflexia. "In preeclampsia, placental stiffness could be increased by higher levels of tissue transglutaminase/TGM2 which catalyzes protein crosslinking." (PMID 38594674, 2024).
prostate tumour (2 papers, 2022 to 2023). "Next, we assessed the expression of both the canonical long form of TG2 (TGM2_v1) and the alternative truncated transcript TGM2_v2, in 57/101 patients’ biopsies after the exclusion of PCA3− biopsies from the prostate tumour group and PCA3+ biopsies from the prostate inflammation group." (PMID 37160910, 2023). "Collectively, these findings demonstrate that TGM2 expression correlates with HIF1A signaling in mice and human prostatic tumors, has potential prognostic value in predicting relapse in patients with PCa, and may thus be used to guide their clinical management." (PMID 35867798, 2022).
Right ventricular hypertrophy (2 papers, 2011 to 2019). In this case the right ventricle is more muscular than normal, causing a characteristic boot-shaped (coeur-en-sabot) appearance as seen on anterior- posterior chest x-rays. "Finally, we confirmed that chronic hypoxia cannot increase vessel wall thickness, the right ventricular systolic pressure (RVSP), and right ventricular hypertrophy index (RVHI) of vascular smooth muscle-specific Tgm2−/− mice." (PMID 32116663, 2019).
steatosis (2 papers, 2022 to 2026). Increased lipid within the cytoplasm of cells. "Thus, we assessed serum levels of neuron-specific enolase (NSE), transglutaminase 2 (TGM2), and glial fibrillary acidic protein (GFAP) as indirect markers of BBB dysfunction and examined their associations with steatosis severity, TNF-α and IL-10 in patients with morbid obesity." (PMID 42195075, 2026). "NSE and GFAP serum levels, but not TGM2, increased proportionally to steatosis stage, showing differences between severe steatosis and no steatosis (p = 0.012 and p = 0.0002, respectively)." (PMID 42195075, 2026).
T-cell lymphoma (2 papers, 2023 to 2024). "In T-cell lymphoma cells, TGM2 up-regulates the IL-6/JAK/STAT3 pathway, which proliferates the growth of T-cell lymphoma cells." (PMID 39115570, 2024).
Tauopathies (2 papers, 2020 to 2025). "Is the CaM-regulated, TGM2-mediated aggregation of pTau a common and critical event in all, or just specific, tauopathies?" (PMID 40867577, 2025).
ulcerative colitis (2 papers, 2022 to 2025). An inflammatory bowel disease involving the mucosal surface of the large intestine and rectum. "For example, the effects of TCA on ulcerative colitis and the role of TGM2 as a target need further experimental validation in animal models and clinical samples." (PMID 41009970, 2025). "TGM2 is a key player in immune response, inflammation, and extracellular matrix repair processes, which are crucial in ulcerative colitis (UC)." (PMID 41009970, 2025).
Age-related cataract (1 paper, 2014). A type of cataract (opacification of the lens) that forms during the course of aging. "Aberrant activation of transglutaminase 2 (TGase2) contributes to a variety of protein conformational disorders such as neurodegenerative diseases and age-related cataracts." (PMID 24481335, 2014).
arterial diseases (1 paper, 2022). "In arterial diseases, transglutaminase 2(TG2) induces β-catenin- and PDGF- signaling in VSMCs, which in turn enhances the proliferative, migratory, and phenotypic switching capacity of these cells." (PMID 36547457, 2022).
candidiasis (1 paper, 2013). Infection with the organism Candida. "Wild type or Tgm2-/- mice infected with SCH1211 succumbed to candidiasis at equal rates and at the same rate as wild type C57BL/6 mice infected with SC5315." (PMID 24260489, 2013).
cervical (1 paper, 2013). "The frequency of TGM2-positive cells, as determined by immunohistochemistry, was also significantly higher in sections of the 19 cervical SCC samples from set 2 that showed OSMR copy number gain, versus the 18 samples that lacked OSMR copy number gain." (PMID 23765377, 2013).
cervical SILs (1 paper, 2013). "TGM2 expression was higher in cervical SILs and SCCs than in normal cervical squamous epithelium 35, while high TGM2 expression in laryngeal SCC was associated with decreased overall survival in patients treated by surgery and radiotherapy." (PMID 23765377, 2013).
Cholestatic liver disease (1 paper, 2024). "In this study, we provide the first evidence that Tgm2 is a crucial factor in DR through governing BMP signalling and plays an indispensable role in cholestatic liver disease." (PMID 38623945, 2024).
chronic lung allograft dysfunction (1 paper, 2022). Chronic lung allograft dysfunction encompasses a range of pathologies that cause a transplanted lung to not achieve or maintain normal function. "Moreover, nintedanib presents a potential anti-oxidative effect in chronic lung allograft dysfunction through downregulation of ROS and transglutaminase-2 (TGM-2)." (PMID 35164664, 2022).
dermatomyositis (1 paper, 2024). Dermatomyositis (DM) is a type of idiopathic inflammatory myopathy characterized by evocative skin lesions and symmetrical proximal muscle weakness. "These include autoantibodies to Histidyl-tRNA synthetase (Jo-1), Anti-Islet Cell Antigen 512 (IA-2), Tissue Transglutaminase 2 (tTG), Dermatomyositis specific autoantigen Mi-2 (Mi-2), thyroid peroxidase (TPO) and SAE1/SAE2." (PMID 39936155, 2024).